GFAP (glial fibrillary acidic protein)
Diseases named in the same sentence as GFAP in open-access papers (continued):
Sharing a sentence is not in itself a finding about the gene and the disease.
cyst (6 papers, 2013 to 2024). A sac-like closed membranous structure that may be empty or contain fluid or amorphous material. "Neurocan expression was confirmed in the cyst area (yellow dotted line) along with GFAP-positive cells." (PMID 38650015, 2024). "The extent of the injury/transplant zone was also identified by the use of GFAP immunostaining, which allows the area of intact spinal cord versus the cyst areas to be defined." (PMID 24070030, 2013). "Cyst size and morphological parameters, including the amount of degenerative tissue immediately surrounding the cyst, were assessed in toluidine blue stained sections and using immunohistochemical assessments of GFAP, β-III tubulin, DcX and GAP43 immunoreactivity at 28 days following SCI." (PMID 25105800, 2014). "GFAP reactive astrocytes at the injury site are not hypertrophic but formed a clear glia layer lining the cyst cavities." (PMID 33469829, 2021).
diabetic neuropathy (6 papers, 2015 to 2025). A chronic, pathological complication associated with diabetes mellitus, where nerve damages are incurred due to diabetic microvascular injury involving small blood vessels that supply these nerves, resulting in peripheral and/or autonomic nerve dysfunction. "This is a rather expected result, because previous works have found that duloxetine alone downregulates increased levels of GFAP found in the spinal cord of mice with diabetic neuropathy." (PMID 37176065, 2023). "Consistent with previous reports in models of diabetic neuropathy, spinal GFAP immunofluorescence was significantly decreased in both the dorsal and the ventral horns of the spinal cord by day 50 in the HFD/STZ model." (PMID 25759824, 2015). "To investigate whether DMF administration inhibited the hyperactivation of microglia and astrocytes, we measured the levels of Iba-1 and GFAP in the spinal cord of mice with STZ-induced diabetic neuropathy." (PMID 34025399, 2021). "A study evaluating circulating GFAP and UCH-L1 levels in patients with and without diabetic polyneuropathy (DPN) found that serum GFAP levels were significantly reduced in individuals with DPN compared to controls and those without DPN." (PMID 41302503, 2025).
Leukoencephalopathy (6 papers, 2012 to 2022). This term describes abnormality of the white matter of the cerebrum resulting from damage to the myelin sheaths of nerve cells. "The Mlc1 gene encodes megalencephalic leukoencephalopathy with subcortical cysts-1 (Mlc1), a membrane protein expressed specifically in GFAP-positive cells in the adult brain." (PMID 29238610, 2017).
multiple system atrophy (6 papers, 2019 to 2025). Multiple system atrophy (MSA) is a neurodegenerative disorder characterized by autonomic failure (cardiovascular and/or urinary), parkinsonism, cerebellar impairment and corticospinal signs with a median survival of 6-9 years. "GFAP also demonstrated the ability to distinguish PSP from multiple system atrophy-parkinsonian type (MSA-P) (AUC = 0.832) and shows a correlation with brainstem atrophy." (PMID 41405696, 2025).
Myelopathy (6 papers, 2020 to 2026). Myelopathy is an descriptive term, referring to pathology leading to a neurologic deficit related to the spinal cord. "Autoimmune glial fibrillary acidic protein (GFAP) astrocytopathy and low-flow perimedullary arteriovenous fistulas (PMAVFs) may cause longitudinal widespread myelopathy." (PMID 38111582, 2023). "This is more commonly seen in idiopathic transverse myelitis (5%), paraneoplastic myelopathy (35%), myelin oligodendrocyte glycoprotein antibody-associated disease (MOGAD), and GFAP-IgG, glycine, and glutamic acid decarboxylase-65 receptor-associated myelopathy." (PMID 36388234, 2022). "There is an important difference between molecular biomarkers such as NfL and GFAP and other (surrogate) outcomes used for myelopathy in ALD." (PMID 33047897, 2020). "Also, because myelopathy in women with ALD has a milder disease course, we hypothesized that NfL and GFAP levels would be lower and associations with disease severity weaker in female compared to male patients." (PMID 33047897, 2020). "We hypothesized that NfL would perform better as biomarker than GFAP, because axonal (and not glial) degeneration is the pathological hallmark of myelopathy in ALD." (PMID 33047897, 2020). "We hypothesized that NfL would be a better biomarker for spinal cord degeneration than GFAP, since axonal rather than glial degeneration is the pathological hallmark of myelopathy in ALD." (PMID 33047897, 2020). "As myelopathy in ALD is characterized by degeneration of the corticospinal tracts and dorsal columns of the spinal cord, we hypothesized that NfL and GFAP could also reflect spinal cord degeneration in ALD." (PMID 33047897, 2020). "In male patients, NfL levels were associated with all three clinical parameters of severity of myelopathy (EDSS, SSPROM, and timed up‐and go), while GFAP in male and NfL and GFAP in female patients were not." (PMID 33047897, 2020).
optic disc edema (6 papers, 2021 to 2025). "In conclusion, GFAP astrocytopathy can cause optic disk edema, which is very often bilateral and can result in blurred vision, though in most cases is asymptomatic, while optic neuritis is very rare." (PMID 39449321, 2024). "Patients with meningoencephalomyelitis and optic disk edema and/or visual disturbances should be tested for GFAP antibodies, particularly when AQP4 and MOG antibodies are negative." (PMID 39449321, 2024). "One previous study described 10 GFAP-Ab-positive patients with bilateral optic disc edema who were typically visually asymptomatic." (PMID 37101204, 2023). "A theory that has been suggested involves the targeting of GFAP in the retina, particularly in the end feet of Müller cells and astrocytes, which can lead to the breakdown of the retina–blood–brain barrier, resulting in optic disk edema." (PMID 39449321, 2024). "Moreover, GFAP astrocytopathy has also been shown to produce optic nerve abnormalities and papillitis." (PMID 39449321, 2024).
ovarian teratoma (6 papers, 2018 to 2025). A non-seminomatous germ cell tumor arising from the ovary. "Another group also reported that an ovarian teratoma associated with coexisting NMDAR and GFAP autoimmune meningoencephalitis in an adolescent girl had extensive CD3 + T cell infiltration." (PMID 37016352, 2023). "Immunohistochemical staining of an ovarian teratoma from a GFAP astrocytopathy patient showed the cytoplasm of the glial process in neuronal tissue and epithelial cells reacted strongly with GFAP-IgG." (PMID 30568655, 2018). "This study presents the first reported case of dual anti-NMDAR and anti-GFAP antibody-positive refractory AE in a 24-year-old female who failed first-line treatments (steroids, IVIG) and ovarian teratoma resection." (PMID 40881715, 2025). "GFAP-IgG antibodies can coexist with anti-NMDAR-IgG, MOG-IgG, and Yo antibodies, but the proportion of concurrent ovarian teratomas was found to be significantly lower than that noted in previous research." (PMID 36552122, 2022). "The co-occurrence of GFAP-IgG, AQP4-IgG, and NMDAR-IgG is a strong predictor of ovarian teratoma." (PMID 40777035, 2025).
post-traumatic stress disorder (6 papers, 2021 to 2026). An anxiety disorder precipitated by an experience of intense fear or horror while exposed to a traumatic (especially life-threatening) event. "Blood-based glial fibrillary acidic protein (GFAP) level within 24 h of traumatic brain injury (TBI) has been inversely associated with post-traumatic stress disorder at 6 months in the Transforming Research and Clinical Knowledge in Traumatic Brain Injury (TRACK-TBI) study." (PMID 40190352, 2025). "Animal models of post-traumatic stress disorders present activation of NLRP3 inflammasome in astrocytes sorted from glial fibrillary acidic protein (GFAP) transgenic mice, while administration of leptin markedly suppressed the activation of astrocytic NLRP3 inflammasome." (PMID 36674935, 2023). "The aims of this project are to examine sex differences in postconcussive, depressive, and post-traumatic stress disorder (PTSD) symptoms, levels of circulating GFAP, tau, NfL, and the relationship between symptoms and biomarkers as well as health-related quality of life (HRQOL)." (PMID 34899299, 2021).
psychosis (6 papers, 2012 to 2025). "Apart from changes in S100B, MDD patients also exhibited elevated levels of soluble GFAP in the cerebrospinal fluid (CSF), while anti-GFAP autoantibodies were found in depressed patients with psychosis." (PMID 39451987, 2024). "In accordance with previously published changes in the GFAP of suicide victims and patients with psychotic disorders, we also found an increased level of GFAP in the amygdala but decreased expression in the cortex." (PMID 23272063, 2012). "In MTLE patients with interictal psychosis, we found increased GFAP expression, especially when compared to the MTLE + D cases, in agreement with a recent hypothesis that astrocyte pathology may be associated with psychotic symptoms, although the exact nature of this change remains unclear." (PMID 25889039, 2015). "Noteworthy, the HPC of patients with temporal lobe epilepsy (TLE) and interictal psychosis present greater GFAP and microglia activation than TLE patients without psychosis." (PMID 38593008, 2024). "A recent study comparing MTLE hippocampi from patients with and without de novo psychosis (postoperative psychosis) analyzed GFAP expression and found no qualitative differences between groups." (PMID 25889039, 2015).
RASopathy (6 papers, 2016 to 2025). Developmental syndromes caused by germline mutations (or in rare cases by somatic mosaicism) in genes that alter the Ras subfamily and mitogen-activated protein kinases that control signal transduction. "The increase of GFAP immunoreactivity in the cortex is supported by previous reports that loss of the RASopathy gene NF1 results in a robust increase in GFAP expression in reactive astrocytes." (PMID 34222248, 2021). "Consistent with other RASopathy-linked mutations, an increased density of GFAP+ astrocytes was observed in Mek1Y130C/Y130C mutant sensory cortices." (PMID 29590634, 2018). "We also found increased GFAP staining, an indicator for reactive gliosis which has also been observed in Rasopathy mouse models." (PMID 41446112, 2025). "Consistently, we found that GFAP expression was significantly higher in cortical spheroids from the RASopathy patient compared with those from a normal control." (PMID 39964758, 2025). "We show that a RASopathy mutation downstream of RAS, Raf1L613V, drives an increase in the number of GFAP+ astrocytes and OPCs." (PMID 31017896, 2019). "Consistent with our findings in Nestin;BRAFKE/+ mice, mouse models carrying the BRAF V600E mutation showed multiple RASopathy-like phenotypes and also exhibited increased GFAP+ cells in the hippocampus and cortex, regardless of their genetic background." (PMID 39964758, 2025). "Interestingly, an increase in GFAP expressing astrocyte-like cells is equally observed in mouse models for RASopathies including neurofibromatosis, Costello syndrome, Noonan syndrome, and cardio-facio-cutaneous syndrome." (PMID 27655340, 2016).
retinal (6 papers, 2018 to 2025). "The increased GFAP, ubiquitous and unspecific response of Müller cells to retinal pathologies and injury, may create a strong adhesion between Müller cells and both ILM and epiretinal tissue." (PMID 29738569, 2018). "Since astrocytic stress is also a common feature of retinal pathologies, we investigated the expression GFAP in astrocytes and Müller glia in APB5 mice with or without minocycline treatment." (PMID 40591415, 2025).
spinal cord disorder (6 papers, 2023 to 2026). A disease involving the spinal cord. "GFAP has been proven to be a highly valuable addition to the biomarker toolbox for early and discriminative diagnosis of brain and spinal cord disorders." (PMID 39289040, 2025). "The comprehensive evaluation of GFAP has the potential to enable longitudinal evaluation of the astrocyte response in brain and spinal cord disorders." (PMID 39289040, 2025). "Previous studies have shown that serum GFAP is elevated in patients with brain or spinal cord diseases compared with healthy controls and is positively correlated with IL-6, a marker of inflammation, in patients with hepatic encephalopathy." (PMID 39459426, 2024). "Nevertheless, serum levels of GFAP are being investigated as a biomarker for brain and spinal cord disorders, and proposed as a differentiating tool between AD and other dementias." (PMID 38600214, 2024). "First, serum GFAP does not appear to predict CNS involvement in AAV as it does in brain and spinal cord diseases." (PMID 39459426, 2024).
uveitis (6 papers, 2007 to 2023). An inflammatory process affecting a part of or the entire uvea. "Notably, upregulated GFAP were also investigated during the pathological changes of uveitis, a typical inflammatory course in the eye." (PMID 38087190, 2023). "During uveitis, Müller glial cells alter their characteristics to become reactive glial cells, leading to breakdown of the blood-retinal barrier with leukocyte infiltration into the vitreous cavity and leukocyte adhesion to the retinal vessels, and it can be recognized by GFAP upregulation." (PMID 29686615, 2018). "We could not detect a clear co-staining of MHC class II with CD31+ endothelial cells or GFAP+ glial cells in the diseased retina, suggesting that, in this model, even during uveitis, endothelial and glial cells mostly do not express MHC class II." (PMID 28720143, 2017).
adenoma (5 papers, 2016 to 2025). A neoplasm arising from the epithelium. "According to their results, it would be of interest whether adenomas with GFAP cytokeratin co-expressing cells are associated with a better clinical prognosis." (PMID 33001343, 2021). "As null cell adenomas are associated with invasive growth, adenomas with GFAP cytokeratin co-expressing cells might be less invasive." (PMID 33001343, 2021). "To investigate the presence and marker expression of enteric glia, we evaluated S100B and GFAP expression in human samples of adjacent normal mucosa, adenoma, and carcinoma tissue from the same CRC patient." (PMID 40580485, 2025). "Correspondingly, among our adenomas with GFAP cytokeratin co-expressing cells, the somatotrophic subtype represents the most frequent one." (PMID 33001343, 2021). "The recurrence rate of adenomas with GFAP and cytokeratin co-expressing cells was lower than the one of pituitary adenomas without co-expression of GFAP and cytokeratin (7.7% vs. 17.8%, p < 0.05)." (PMID 33001343, 2021). "The area with overlapping expression of GFAP and cytokeratin was 2.6% for both, adenoma and normal pituitary." (PMID 33001343, 2021). "Furthermore, adenomas with cellular co-expression of GFAP and cytokeratin were associated with a lower recurrence rate (7.7%) compared to adenomas without co-expression of intermediate filaments (17.8%)." (PMID 33001343, 2021). "Healthy, adenoma, and tumor tissues from CRC patients were immunohistochemically stained for the glial markers S100B and glial fibrillary acidic protein (GFAP)." (PMID 40580485, 2025). "GFAP-positive enteric glia were identified within carcinoma tissue stroma but were absent in normal mucosa or adenoma tissue from the same patients." (PMID 40580485, 2025). "Of note, we showed that normal mucosa and adenoma tissue harbor S100B-positive enteric glia that are not immunoreactive for GFAP." (PMID 40580485, 2025). "No null cell adenoma was found among the group of adenomas with cellular co-expression of GFAP and cytokeratin." (PMID 33001343, 2021). "Depleting GFAP+ enteric glia resulted in a profoundly reduced tumor burden in AOM/DSS mice and additionally reduced adenomas in the ApcMin/+ mouse model of familial adenomatous polyposis, suggesting a tumor-promoting role for these cells at an early premalignant stage." (PMID 33282743, 2020). "Positive staining for NES, GFAP, and A2B5 in untreated cell samples made us conclude that these cells already possess the features of these cell types because of partial differentiation most probably into adenoma tissue." (PMID 27340409, 2016). "Moreover, we observed that GFAP expression, one of the hallmarks of enteric gliosis, was absent from glia in normal mucosa and rarely found in adenoma tissue." (PMID 40580485, 2025). "However, GFAP staining was absent in normal mucosal tissue (0 of 8 patients), rarely found in adenoma tissue (staining in 1 of 8 patients), but abundantly present in carcinoma tissue (staining in 6 of 8 patients)." (PMID 40580485, 2025). "Since we observed S100B-expressing enteric glia in normal mucosa, adenoma and carcinoma tissue, we hypothesize that these cells represent mucosal enteric glia that upregulate GFAP, rather than cells that migrated centripetally from outer plexus layers into the tumor." (PMID 40580485, 2025).
Arthritis (5 papers, 2015 to 2024). Inflammation of a joint. "The reactivity of astrocytes in the spinal tissue of mice in arthritis models has been demonstrated specifically using glial fibrillary acidic protein (GFAP) staining as a biomarker." (PMID 36387416, 2022). "Moreover, in an adjuvant-induced arthritis model, astrocytes expressing GFAP were increased in number and immunostaining intensity in the spinal cord and were associated with increased levels of cytokines such as IL-1β, IL-6, and TNF." (PMID 36387416, 2022). "Recently, it was reported that antisense oligodeoxynucleotides specifically against NT-3 intrathecally administered could suppress expression of spinal GFAP, OX-42, and proinflammatory cytokines stimulated with arthritis." (PMID 26161124, 2015).
diffuse astrocytoma (5 papers, 2020 to 2025). A low-grade (WHO grade II) astrocytic neoplasm. "The double staining for GFAP/ATRX demonstrates that reactive astrocytes retain ATRX expression in the nucleus (i.e., with ATRX-wild type), whereas in diffuse astrocytomas, tumor astrocytes are ATRX-mutant." (PMID 32599896, 2020).
ependymal tumor (5 papers, 2007 to 2021). A group of neoplasms which arise from the ependymal lining of the cerebral ventricles and from the remnants of the central canal of the spinal cord. "Immunohistochemistry showed that ependymal tumors were positive for GFAP." (PMID 34065573, 2021). "Expression of particular markers differentially expressed in astrocytic and in ependymal neoplasms revealed low OLIG2 and SOX10 expression (adjusted p = 3.89e − 26 and adjusted p = 7.75e − 65) within the novel group, with similar expression of GFAP (online resource)." (PMID 34355256, 2021). "GFAP and EMA, which are negative in neuronal tumors, are positive in ependymal tumors, although this can be focal." (PMID 17626628, 2007).
hemangioblastoma (5 papers, 2016 to 2025). "Hemangioblastomas are usually positive for alpha-inhibin, D2-40, brachyury, NSE, NCAM1, S100, ezrin, CXCR4, aquaporin-1, and occasionally for GFAP and EGFR, and negative for EMA, CD10 and CAM5.2." (PMID 41302074, 2025).